REST (RE1 silencing transcription factor)
Description:
Transcriptional repressor which binds neuron-restrictive silencer element (NRSE) and represses neuronal gene transcription in non-neuronal cells. Restricts the expression of neuronal genes by associating with two distinct corepressors, SIN3A and RCOR1, which in turn recruit histone deacetylase to the promoters of REST-regulated genes. Mediates repression by recruiting the BHC complex at RE1/NRSE sites which acts by deacetylating and demethylating specific sites on histones, thereby acting as a chromatin modifier (By similarity). Transcriptional repression by REST-CDYL via the recruitment of histone methyltransferase EHMT2 may be important in transformation suppression. Represses the expression of SRRM4 in non-neural cells to prevent the activation of neural-specific splicing events and to prevent production of REST isoform 3 (By similarity). Repressor activity may be inhibited by forming heterodimers with isoform 3, thereby preventing binding to NRSE or binding to corepressors and leading to derepression of target genes. Also maintains repression of neuronal genes in neural stem cells, and allows transcription and differentiation into neurons by dissociation from RE1/NRSE sites of target genes (By similarity). Thereby is involved in maintaining the quiescent state of adult neural stem cells and preventing premature differentiation into mature neurons. Plays a role in the developmental switch in synaptic NMDA receptor composition during postnatal development, by repressing GRIN2B expression and thereby altering NMDA receptor properties from containing primarily GRIN2B to primarily GRIN2A subunits (By similarity). Acts as a regulator of osteoblast differentiation (By similarity). Key repressor of gene expression in hypoxia; represses genes in hypoxia by direct binding to an RE1/NRSE site on their promoter regions. May also function in stress resistance in the brain during aging; possibly by regulating expression of genes involved in cell death and in the stress response. Repressor of gene expression in the hippocampus after ischemia by directly binding to RE1/NRSE sites and recruiting SIN3A and RCOR1 to promoters of target genes, thereby promoting changes in chromatin modifications and ischemia-induced cell death (By similarity). After ischemia, might play a role in repression of miR-132 expression in hippocampal neurons, thereby leading to neuronal cell death (By similarity). Negatively regulates the expression of SRRM3 in breast cancer cell lines. [Isoform 3]: Binds to the 3' region of the neuron-restrictive silencer element (NRSE), with lower affinity than full-length REST isoform 1 (By similarity). Exhibits weaker repressor activity compared to isoform 1. May negatively regulate the repressor activity of isoform 1 by binding to isoform 1, thereby preventing its binding to NRSE and leading to derepression of target genes. However, in another study, does not appear to be implicated in repressor activity of a NRSE motif-containing reporter construct nor in inhibitory activity on the isoform 1 transcriptional repressor activity. Post-transcriptional inactivation of REST by SRRM4-dependent alternative splicing into isoform 3 is required in mechanosensory hair cells in the inner ear for derepression of neuronal genes and hearing (By similarity).
Synonyms: NRSF; XBR; DFNA27; GINGF5; HGF5; WT6
Tractability: PROTAC: UniProt records ubiquitination sites on it; ubiquitination databases record sites on it.
Gene: Protein-coding gene on chromosome 4 (56,907,876 to 56,966,808, forward strand). Ensembl gene ENSG00000084093.
Subcellular location: Nucleus; Cytoplasm; Cytoplasm (Isoform 2); Nucleus (Isoform 3); Cytoplasm (Isoform 4)
Subcellular location (Human Protein Atlas): Nucleoplasm; Cytosol
Pathways (Reactome):
Signal Transduction: NGF-stimulated transcription; Regulation of PTEN gene transcription
Chromatin organization: HDACs deacetylate histones
Disease: Potential therapeutics for SARS
Gene expression (Transcription): Regulation of NPAS4 gene transcription
Gene Ontology:
Molecular function: DNA-binding transcription factor activity; DNA-binding transcription repressor activity, RNA polymerase II-specific; protein binding; RNA polymerase II cis-regulatory region sequence-specific DNA binding; RNA polymerase II-specific DNA-binding transcription factor binding; transcription cis-regulatory region binding; chromatin binding; DNA binding; RNA polymerase II core promoter sequence-specific DNA binding; sequence-specific DNA binding
Biological process: cellular response to electrical stimulus; cellular response to glucocorticoid stimulus; host-mediated suppression of viral transcription; negative regulation of aldosterone biosynthetic process; negative regulation of amniotic stem cell differentiation; negative regulation of cortisol biosynthetic process; negative regulation of DNA-templated transcription; negative regulation of insulin secretion; negative regulation of mesenchymal stem cell differentiation; negative regulation of miRNA transcription; negative regulation of neuron differentiation; negative regulation of transcription by RNA polymerase II; nervous system process; positive regulation of DNA-templated transcription; positive regulation of stem cell population maintenance; response to hypoxia; cardiac muscle cell myoblast differentiation; chromatin remodeling; modification of synaptic structure; negative regulation of calcium ion-dependent exocytosis; negative regulation of dense core granule biogenesis; negative regulation of neurogenesis; neuronal stem cell population maintenance; positive regulation of neuron differentiation; positive regulation of programmed cell death; and 7 more
Cellular component: cytoplasm; cytosol; nucleoplasm; nucleus; transcription repressor complex
Genetic constraint (gnomAD): Loss-of-function variants: 1 observed, 29.73 expected, observed/expected ratio (o/e) 0.0336, 90% interval 0.011 to 0.16. The upper end of that interval is the gene's LOEUF score, 0.16, which puts it in group 1 of 6, group 1 being the genes least tolerant of losing a copy. Missense variants: 1,237 observed, 1,360.7 expected, observed/expected ratio (o/e) 0.91, 90% interval 0.87 to 0.95. Synonymous variants: 487 observed, 465.51 expected, observed/expected ratio (o/e) 1.05, 90% interval 0.97 to 1.13.
Homologues: Orthologues: chimpanzee REST (98% identical), macaque REST (95% identical), dog REST (74% identical), rabbit REST (66% identical), rat Rest (66% identical), mouse Rest (65% identical), tropical clawed frog rest (44% identical), zebrafish rest (30% identical), Drosophila melanogaster hb (8% identical), Drosophila melanogaster CG12391 (7% identical), Caenorhabditis elegans Y5F2A.4 (5% identical), Caenorhabditis elegans hbl-1 (5% identical). Paralogues in human: PEG3 (9% identical), ZNF518A (9% identical), ZKSCAN2 (7% identical), ZNF770 (7% identical), ZNF18 (7% identical), ZSCAN29 (7% identical), ZBTB35 (7% identical), ZNF274 (7% identical), ZSCAN32 (7% identical), ZSCAN5C (7% identical), ZSCAN5A (7% identical), ZNF518B (6% identical), and 17 more.
Diseases named in the same sentence as REST in open-access papers:
REST is named in the same sentence as 209 diseases in open-access papers, as found by Europe PMC text mining. Sharing a sentence is not in itself a finding about the gene and the disease. The quoted sentences say what the papers report.
Alzheimer disease (42 papers, 2009 to 2025). A progressive, neurodegenerative disease characterized by loss of function and death of nerve cells in several areas of the brain leading to loss of cognitive function such as memory and language. "The scenario varies in the aging neurons, as lower REST expression protects such neurons and, in many cases, loss of REST expression leads to Alzheimer’s disease." (PMID 40006989, 2025). "Transcription factor REST has been associated with the preservation of cognition in Alzheimer’s disease, dementia with Lewy bodies, and FTD." (PMID 34720873, 2021). "Recently, REST (RE1-silencing transcription factor) gene has been shown to be lost in Alzheimer’s disease (AD), and a missense minor REST allele rs3796529-T has been shown to reduce the rate of hippocampal volume loss." (PMID 30705771, 2019). "REST contributes to shaping neuronal development and function and it has also been implicated in the pathogenesis of neurological disorders such as epilepsy, Alzheimer's disease and Huntington's disease." (PMID 38739758, 2024). "In aging neurons, REST loss is associated with the onset of Alzheimer’s disease in humans." (PMID 33804468, 2021). "Dysregulation of REST has also been implicated in the pathogenesis of Huntington disease and Down syndrome and was shown to be involved in stress resistance in aging and Alzheimer's disease." (PMID 30510498, 2018). "Potential roles for REST and CoREST in modulating the specific profiles of neuronal loss in neurodegenerative diseases are further suggested by our finding that REST and CoREST targeted a number of Alzheimer's disease associated genes." (PMID 19997604, 2009). "In Alzheimer’s disease (AD), REST expression is diminished in regions of extensive oxidative damage, suggesting a protective role of REST in mitigating the harmful effects of excitatory transmission during aging." (PMID 40136528, 2025). "The transcription factor REST is dysregulated in several neurodegenerative diseases, such as Alzheimer’s disease and Parkinson’s disease." (PMID 39178947, 2024). "REST is upregulated under stress signals, aging and neurodegenerative diseases, but although it is upregulated, its function is lost in Alzheimer’s Disease." (PMID 39511137, 2024). "This article looks at the role of REST and the influence of various microRNAs in controlling REST function in the progression of Alzheimer’s disease (AD), Parkinson’s disease (PD), and Huntington’s disease (HD) disease." (PMID 37326903, 2023). "Here, the authors describe a neurodegeneration checkpoint response mediated by the transcription factor REST that protects against the onset of Alzheimer’s disease." (PMID 37919281, 2023). "Age-hypermethylated sites in PBMCs have been previously shown to be enriched for REST, which is known to repress stress response genes and is lost in cognitive impairment and Alzheimer’s disease pathology." (PMID 37589453, 2023). "REST is neuroprotective in aged human neurons, iPSC-derived neurons in patients with Alzheimer’s disease (AD), and in mouse models of AD." (PMID 35406743, 2022). "Recently, emerging evidence has suggested that REST expression and activity are decreased in Alzheimer’s disease and Parkinson’s disease, and that neuron apoptosis caused by REST downregulation contributes to these pathological process." (PMID 35418568, 2022). "Repressor element 1-silencing transcription (REST)/neuron-restrictive silencer factor is considered a new therapeutic target for neurodegenerative disorders such as Alzheimer’s disease (AD)." (PMID 35650520, 2022). "In Alzheimer’s disease, oxidative stress activates neuronal autophagosomes which can engulf REST together with other misfolded proteins, such as Aβ and tau." (PMID 33185010, 2021). "We quantified changes in nuclear REST expression in the brains of ageing wild‐type (WT) and Alzheimer’s disease (AD) rats." (PMID 33185010, 2021).
Alzheimer disease (continued). "Here, we examined the spatiotemporal immunolocalisation of REST in the brains of healthy ageing wild‐type Fischer‐344 and transgenic Alzheimer’s disease rats (TgF344‐AD)." (PMID 33185010, 2021). "Recent evidence supports a protective role of REST in CNS diseases: REST is neuroprotective in aging and counteracts the development of Alzheimer’s disease by protecting neurons from oxidative stress and amyloid β-induced toxicity." (PMID 33589593, 2021). "In contrast, inability to upregulate nuclear REST is thought to leave ageing neurons vulnerable to neurodegenerative stimuli, such as Alzheimer’s disease (AD) pathology." (PMID 33185010, 2021). "Changes in expression of REST have been shown to correlate with mild cognitive disorders and Alzheimer's disease." (PMID 30510498, 2018). "Other recent studies also suggest that REST is induced in the aging brain but markedly depleted in the nucleus of neurons in Alzheimer’s disease, frontotemporal dementia and dementia with Lewy bodies." (PMID 28515679, 2017). "REST protein also protects aging neurons from death by repressing genes that promote cell death and Alzheimer’s disease (AD) pathology and inducing the expression of stress response genes." (PMID 28515679, 2017). "Compared to the studies on Alzheimer’s disease, those related to the role of REST in the Parkinson’s disease appear less conclusive." (PMID 26465007, 2015). "It was reported that REST expression is a protective factor in aging and is decreased in neurodegenerative diseases such as Alzheimer’s disease." (PMID 26341630, 2015). "In contrast in the brains of those with Alzheimer's disease, both Wnt signaling and REST induction are suppressed, leading to neurodegeneration." (PMID 26690059, 2015). "REST enhances TH expression, protects dopaminergic neurons from Mn toxicity, reduces oxidative stress, regulates apoptosis, promotes antioxidants, and its dysfunction links to Parkinson’s and Alzheimer’s disease." (PMID 40278152, 2025). "With aging, there is always present low level of REST gene expression in the neurons because its absence may fuel Alzheimer’s disease." (PMID 35538578, 2022). "Because the RE1-silencing transcription factor (REST) as another nuclear transcription factor works against the oxidative stress of aging brain and Alzheimer's Disease using immunostaining of human brain, we tested the expression level of REST and it was not clearly changed." (PMID 34168538, 2021). "Moreover, growing evidence based on data from patients with Alzheimer's disease (AD) or Parkinson's disease (PD), and animal models thereof has indicated the decreased expression and activity of REST under pathological conditions." (PMID 34520100, 2021). "Therefore, we investigated the spatiotemporal localisation of REST in healthy ageing and Alzheimer’s disease rat brains." (PMID 33185010, 2021). "However in Alzheimer ́s disease REST is lost from the nucleus, and then it appears in the cytoplasm of autophagosomes, along with pathologically misfolded proteins." (PMID 31361762, 2019). "REST is reduced in stress conditions and in patients with Alzheimer's disease (AD), which suggests that increasing REST could be neuroprotective." (PMID 31361762, 2019). "REST is lost in mild cognitive impairment and Alzheimer's disease; chromatin immunoprecipitation analyses using deep sequencing (ChIP-seq) and expression analyses show that REST genes promote cell death and AD pathology, and induce the expression of stress response genes." (PMID 31361762, 2019). "The repressor element 1-silencing transcription (REST) factor, alternatively named neuron-restrictive silencing factor (NRSF), is a protein that modulates neuronal differentiation and gene expression, and has recently been found to play an important role in Alzheimer’s disease (AD) neuropathology." (PMID 28585932, 2017).
Alzheimer disease (continued). "Because a REST coding variant (rs3796529) was previously associated with protection from hippocampal atrophy in elderly subjects with mild cognitive impairment (MCI), we analyzed a cohort of Alzheimer disease (AD) continuum patients." (PMID 28842657, 2017). "In this model, REST induction suppresses neuronal apoptotic cell death and the toxic effects of the accumulation of amyloid-β (Aβ, the main protein component of the plaques found in the brains of patients with Alzheimer's disease)." (PMID 26690059, 2015). "Two interesting studies recently rejuvenated interest in the role of REST in Alzheimer’s disease." (PMID 26465007, 2015). "Finally, our list also included NRSF/REST, which has a role in suppressing genes which promote Alzheimer’s disease." (PMID 25692570, 2015). "Moreover, changes of neuronal REST levels had been reported during human aging, in various forms of cancer, and in several brain diseases, including Alzheimer's disease and epilepsy." (PMID 26617488, 2015). "Also, while the loss of REST function has been linked recently to the development of Alzheimer’s disease, a consistent mechanism for the loss of REST has not been identified." (PMID 39314474, 2024). "Repressor element 1-silencing transcription factor (REST), a transcription factor (TF), also known as neuron-restrictive silencer factor, has been shown to exert neuroprotection in several animal models of neurodegenerative diseases, including PD and Alzheimer’s disease (AD)." (PMID 39178947, 2024). "Interestingly, however, various factors now recognized as being REST dependent, such as miRNAs (including miR-9/9* and miR-132, which operate reciprocally to REST) and ncRNAs, have been proposed to play significant roles in Alzheimer’s disease." (PMID 26465007, 2015). "In particular, low exosomal levels of survival factors (i.e., LRP6, REST, and HSF1) were found in Alzheimer's disease." (PMID 28912682, 2017). "Intriguingly, similar to the absence of its nuclear localization in leiomyoma, REST is lost from the nuclei of neurons in Alzheimer’s disease, instead appearing in autophagosomes along with pathological misfolded proteins." (PMID 39314474, 2024). "REST expression, however, does not change with age in the TgF344‐AD rat model of Alzheimer’s disease." (PMID 33185010, 2021). "For many years, intensive studies of the mechanisms of the pathogenesis of Alzheimer’s disease, which affects a considerable fraction of elderly humans, did not consider the possible involvement of REST." (PMID 26465007, 2015). "Of note, nuclear REST levels do not increase in aging humans with brain diseases, especially in patients with Alzheimer’s disease (see the discussion in the Alzheimer’s disease section)." (PMID 26465007, 2015). "In other areas of the brain, such as the dentate gyrus and the cerebellum, that are not affected by Alzheimer’s disease, the concentration of REST in nuclei was as high as in control subjects." (PMID 26465007, 2015). "Moreover, low exosomal levels of LRP6, REST, HSF1 were found in Alzheimer's disease." (PMID 28912682, 2017).